NPTX2 (neuronal pentraxin 2)
Diseases named in the same sentence as NPTX2 in open-access papers (continued):
Sharing a sentence is not in itself a finding about the gene and the disease.
Anxiety (6 papers, 2018 to 2025). Intense feelings of nervousness, tension, or panic often arise in response to interpersonal stresses. "Previous studies have suggested that the expression of the Nptx2 gene is associated with anxiety, but the neurobiological processes underlying this association remain unclear." (PMID 29844474, 2018). "NPTX2 has been reported to play a role in the regulation of anxiety and cognitive function, but its role in islet biology is warranted for further study." (PMID 39345556, 2024). "Some members of the pentraxin gene family that we found to be modulated here (Nptxr|Nptx1|Nptx2) are involved in anxiety and responses to stress, which support their modulation in stressed animals." (PMID 36890154, 2023). "To investigate the relationship between Nptx2 and anxiety, we subjected mice to a battery of behavioral tests (WT, n = 24; cKO, n = 21)." (PMID 29844474, 2018). "In this study, we generated loxP-flanked Npxt2 knockout (KO) mice to examine the role of Nptx2 on anxiety." (PMID 29844474, 2018). "We generated multiple mouse models with knockout or overexpression of Nptx2 in specific brain regions and during different developmental stages to assess anxiety, adult neurogenesis, and glucocorticoid-related gene expression." (PMID 29844474, 2018). "We utilized three gene deletion methods to examine the role of Nptx2 in anxiety: central nervous system-specific, tamoxifen-induced, and hippocampus-specific deletion." (PMID 29844474, 2018). "Our results provide evidence that Nptx2 expression in the adult hippocampus regulates anxiety in mice." (PMID 29844474, 2018). "Our work provides a multi-pronged approach to clearly delineate the role of Nptx2 in stress and anxiety." (PMID 29844474, 2018). "Since Nptx2 is expressed in amygdala, we examined the contribution of amygdala Nptx2 in anxiety via injecting AAV-Cre or AAV-eGFP viral vectors into the amygdala in Nptx2f/f mice (n = 8)." (PMID 29844474, 2018). "Eliminating Nptx2 expression in either the developing mouse brain or in adulthood leads to increased anxiety levels." (PMID 29844474, 2018). "In conclusion, our results indicate that hippocampal Nptx2 plays a critical role in modulating anxiety, altering stress sensitivity, and influencing the expression of GR downstream genes." (PMID 29844474, 2018). "To study the potential of Nptx2 to be a target for novel treatments for anxiety, we overexpressed Nptx2 in the hippocampus." (PMID 29844474, 2018). "Altogether, these results further demonstrate that Nptx2 plays an important role in mediating anxiety." (PMID 29844474, 2018). "In conclusion, we demonstrate that Nptx2 in the hippocampus performs a critical role in modulating anxiety, hippocampal cell proliferation, and glucocorticoid receptor related gene expression." (PMID 29844474, 2018). "To determine the mechanism through which Nptx2 alters anxiety, we assessed differences in hippocampal gene expression between brain-specific Nptx2 cKO and WT mice by RNA-sequencing (RNAseq; n = 3)." (PMID 29844474, 2018). "Our data suggest that hippocampal Nptx2 plays a critical role in regulating anxiety, progenitor cell proliferation, and the expression of genes that underlie the glucocorticoid response." (PMID 29844474, 2018). "Thus, our study provides strong evidence that hippocampal Nptx2 regulates anxiety and reveals it as a potential target for novel treatments for stress-related anxiety disorders." (PMID 29844474, 2018). "This suggests increased Nptx2 is protective against stress-induced anxiety." (PMID 29844474, 2018). "These factors also influence neurogenesis and emotional responses, thus we hypothesize that Nptx2 may play roles in neurogenesis or anxiety." (PMID 29844474, 2018). "Our data show that brain-specific Nptx2 KO mice exhibit increased anxiety." (PMID 29844474, 2018). "Overall, our results showed that Nptx2 deletion robustly increased anxiety-like behaviors." (PMID 29844474, 2018).
Anxiety (continued). "Because C57BL/6 is one of the least anxious inbred mouse strains, we tested whether increased Nptx2 can reduce anxiety following stress." (PMID 29844474, 2018). "Since chronic antidepressant treatment or exercise upregulates Nptx2 expression in the hippocampus and Nptx2-deficient mice display more c-Fos-positive cells in the DG and CA3 regions but not the amygdala after acute stress, we hypothesized that hippocampal Nptx2 modulates anxiety behavior." (PMID 29844474, 2018). "Altogether, these data suggest that Nptx2 expression in the hippocampus, but not the amygdala, plays a critical role in anxiety-related behaviors." (PMID 29844474, 2018). "Our experiments demonstrate that the effects of Nptx2 deletion on anxiety-like behavior are hippocampus-specific and not developmentally related." (PMID 29844474, 2018). "The data we present here suggests that the anxiety phenotype is independent of neurogenesis in Nptx2 KO mice." (PMID 29844474, 2018). "The increase in anxiety was evident in hippocampus-specific Nptx2 knockout mice, but not in an amygdala specific knockouts." (PMID 29844474, 2018). "To date, not much is known about the role of NPTX2 in anxiety." (PMID 29844474, 2018).
schizophrenia (6 papers, 2016 to 2025). A major psychotic disorder characterized by abnormalities in the perception or expression of reality. "Analyses of prefrontal cortex tissues from schizophrenia patients have reported significant reductions in the expression of genes associated with the GABAergic system, such as NPTX-2 and parvalbumin." (PMID 40563435, 2025). "In disorders characterized by excitatory–inhibitory imbalance, such as schizophrenia, decreased levels of NPTX-2 have also been demonstrated." (PMID 40563435, 2025). "Changes in NPTX-2 levels have also been demonstrated in neuropsychiatric disorders such as epilepsy and schizophrenia." (PMID 40563435, 2025). "As well, Nptx2 has been shown to be decreased in the post-mortem brains of people with AD and in the cerebrospinal fluid of patients with schizophrenia." (PMID 37763230, 2023).
amyloidosis (5 papers, 2017 to 2020). A disorder characterized by the localized or diffuse accumulation of amyloid protein in various anatomic sites. "Both amyloid and NPTX2 result in reduced PV interneuron function and a consequent increase of excitability of pyramidal neurons that are part of the reciprocal circuits with PV interneurons." (PMID 28440221, 2017). "They found that mice with amyloidosis and deletion of the NPTX2 gene had lower levels of GluA4 and more defects in circuit activity than mice with just amyloidosis alone." (PMID 28440224, 2017). "In a mouse model of AD amyloidosis, Nptx2-/- results in reduced GluA4 expression, disrupted rhythmicity, and increased pyramidal neuron excitability." (PMID 28440221, 2017). "We examined the consequence of NPTX2 reduction in a mouse model of AD and found that amyloidosis together with Nptx2-/- results in a synergistic reduction of inhibitory circuit function in conjunction with a reduction of the AMPA type glutamate receptor GluA4." (PMID 28440221, 2017). "Our model predicts that the combined action of amyloidosis and NPTX2 down-regulation will produce a disruption of the dynamic recruitment of pyramidal neuron-PV interneuron circuits." (PMID 28440221, 2017). "GluA4 is further reduced in AD by NPTX2 down-regulation in the context of amyloidosis." (PMID 28440221, 2017). "Because of the synergistic effects of amyloidosis and NPTX2 down regulation, CSF levels of NPTX2 might distinguish subjects who will be most responsive to amyloid reducing therapy." (PMID 28440221, 2017). "However, the consequence of amyloid and NPTX2 down-regulation on pyramidal neuron-PV interneuron circuits appear quite different." (PMID 28440221, 2017). "To assess the possible impact of NPTX2 down-regulation in human AD brain, we created a mouse model that combines amyloidosis (APPswe/PS1∆E9; here termed hAPP) and Nptx2-/-." (PMID 28440221, 2017). "For example, slice recordings from genetically modified adult mice lacking NPTX2 show near normal gamma oscillation frequency and power; however, in combination with a transgene that generates amyloidosis, these mice have a profound reduction of gamma power." (PMID 31231205, 2019). "NPTX2 is not down-regulated in a widely used mouse amyloidosis model and is distinct from other CSF markers attributed to neurodegeneration including tau and p-tau in that NPTX2 is an indicator of specific rather than general excitatory synapses." (PMID 28440221, 2017).
clear cell renal cell carcinoma (4 papers, 2022 to 2025). "Novel findings from RCC preclinical models reveal that MANF protein drives sunitinib resistance via IRE1α-XBP1 pathway inhibition, while NPTX2 aberrantly activates PI3K-Akt survival signaling in clear cell renal cell carcinoma (ccRCC)." (PMID 41142779, 2025).
gastric cancer (4 papers, 2017 to 2025). A primary or metastatic malignant neoplasm involving the stomach.
renal cell carcinoma (4 papers, 2020 to 2025). "NPTX2 overexpression promotes the cell proliferation, migration and invasion of renal cell carcinoma." (PMID 33768003, 2021).
vascular dementia (4 papers, 2020 to 2023). A degenerative vascular disorder affecting the brain. "One study looked for a correlation between serum level NPTX2 level and MOCA scores in patients with vascular dementia and find a positive correlation between them (R = 0.347, p = 0.042)." (PMID 36793451, 2023).
Down syndrome (3 papers, 2017 to 2025). "CSF NPTX2 concentration was lower (fold change [FC] 0.82, p < 0.01) in AD patients and Down syndrome individuals (FC 0.56, p < 0.001), compared with cognitively unimpaired patients (CU)." (PMID 40522075, 2025). "The authors developed a novel digital automated emzyne‐linked immunosorbent assay (ELISA) on the Simoa platform to measure NPTX2 in CSF, both in AD patients and individuals with Down syndrome (DS)." (PMID 40522075, 2025). "Furthermore, this work opens the door to future studies exploring the potential of CSF NPTX2 as a prognostic marker for late-onset myoclonic epilepsy in Down syndrome and sporadic AD." (PMID 32807227, 2020).
glioma (3 papers, 2014 to 2021). A benign or malignant brain and spinal cord tumor that arises from glial cells (astrocytes, oligodendrocytes, ependymal cells). "In agreement with our sequencing results, three of the five lncRNAs (TCONS_l2_00004574, uc031tga.1, and uc022adp.1) and four of the five mRNAs (NPTX2, HIST2H3C, MMP10, and HIST1H1B) were found to be differentially expressed in the glioma samples (P < 0.05)." (PMID 32211318, 2020). "NPTX2 has been shown to be overexpressed in edematous versus nonedematous gliomas in the absence of increased VEGF expression." (PMID 24804210, 2014).
lung carcinoma (3 papers, 2021 to 2024). "Six DMRs located on HOXA9, HOXD3, PCDH17, NID2, NPTX2, and SFRP2 genes exhibiting clinical accuracy over 75% irrespective of lung cancer subtype and cancer progression stages were selected as lung cancer-specific exosome DNA methylation biomarkers." (PMID 39123492, 2024).
narcolepsy (3 papers, 2009 to 2020). A sleep disorder characterized by a tendency for excessive sleepiness during the day which occurs even after adequate sleep in the nighttime. "Interestingly, a substantial loss of hypothalamic cells producing hypocretin, PDYN and NPTX2 has been found in patients with narcolepsy." (PMID 32552841, 2020). "The overlap in symptoms might suggests a common etiology between DLB and narcolepsy and indicates that PDYN and NPTX2 reduction may be important biological substrates underlying sleep-related symptoms in DLB." (PMID 32552841, 2020).
prostate carcinoma (3 papers, 2022 to 2024). A carcinoma that arises from epithelial cells of the prostate gland. "In conclusion, our study demonstrated that NPTX2 acts as a tumor suppressor gene in prostate cancer." (PMID 35069913, 2022). "In conclusion, this is the first report showing that NPTX2 expression is epigenetically silenced in prostate cancer due to DNA methylation of the NPTX2 promoter." (PMID 35069913, 2022). "The results showed that expression of NPTX2 in control cells was higher than that in several prostate cancer cell lines." (PMID 35069913, 2022). "Consistent with the in vitro results, restoring the expression of NPTX2 inhibited prostate tumor growth in vivo, demonstrating that NPTX2 is a key inhibitor of tumorigenesis in prostate cancer." (PMID 35069913, 2022). "To further confirm that the low expression of NPTX2 in prostate cancer is due to promoter methylation, we treated DU145, PC3 and C4-2 cell lines with the demethylating agent 5-aza-2′-deoxycytidine (5-AZA-dC)." (PMID 35069913, 2022). "This evidence suggested that the NPTX2 promoter is methylated and that its expression is inhibited in prostate cancer cells." (PMID 35069913, 2022). "NPTX2 mRNA expression levels were negatively correlated with NPTX2 promoter methylation in a cohort of prostate cancer patients in the TCGA Research Network (n = 497)." (PMID 35069913, 2022). "Herein, we found that NPTX2 is significantly reduced in prostate cancer tissues and cancer cell lines compared to control prostate tissues and control prostatic epithelial cell lines." (PMID 35069913, 2022). "It is important to improve expression levels of NPTX2 in prostate cancer, and the most straightforward approach for doing this is to remove promoter methylation." (PMID 35069913, 2022). "NPTX2, which is silenced in prostate cancer but highly expressed in control prostate tissues, has great potential research value." (PMID 35069913, 2022). "Furthermore, decitabine inhibited the proliferation-promoting effect of neuronal pentraxin 2 mediated via its methylation in prostate cancer cells." (PMID 38988323, 2024). "It has been reported that neuronal pentraxin 2 expression is significantly reduced in prostate cancer tissues and cancer cell lines, which may be due to the high methylation of the neuronal pentraxin 2 promoter." (PMID 38988323, 2024). "Furthermore, our results suggested that NPTX2 inhibits prostate cancer tumor growth in vitro and in vivo." (PMID 35069913, 2022). "Understanding the silencing mechanism of NPTX2 and reversing this low expression status may be of great significance for the treatment of prostate cancer." (PMID 35069913, 2022). "Overexpression of NPTX2 inhibited prostate cancer cell proliferation both in vitro and in vivo." (PMID 35069913, 2022). "Additionally, the detailed clinical parameters of the enrolled patients are shown in TCGA database, which demonstrated that the expression of NPTX2 in prostate cancer was significantly lower than that in control tissues (p < 0.05)." (PMID 35069913, 2022). "As mentioned in the results section, TCGA data and our experimental studies, MSP, qPCR, western blot, and prostate cancer cells treated with 5-AZA-dC confirmed that NPTX2 expression in prostate cancer tissues was lower than that in control prostate tissues due to promoter methylation." (PMID 35069913, 2022). "Furthermore, we performed qPCR and western blot assays to determine the expression of NPTX2 in several prostate cancer cell lines, C4-2, LNCaP, DU145, and PC3, and the control prostatic epithelial cell line RWPE-1." (PMID 35069913, 2022). "In this study, we aimed to explore the role and potential mechanism of NPTX2 in prostate cancer." (PMID 35069913, 2022). "Therefore, we hypothesized that DNA hypermethylation might be responsible for the downregulation of NPTX2 in prostate cancer." (PMID 35069913, 2022). "Furthermore, the NPTX2 promoter is highly methylated in prostate cancer cells." (PMID 35069913, 2022).
prostate carcinoma (continued). "However, whether NPTX2 is involved in prostate cancer progression is unclear." (PMID 35069913, 2022).
Brain atrophy (2 papers, 2018 to 2025). Partial or complete wasting (loss) of brain tissue that was once present. "Nptx2 is a novel proinflammatory cytokine that can predict AD correlation, which is better than any other immunological marker, and is mainly related to brain atrophy, especially memory decline." (PMID 30245729, 2018).
chronic pancreatitis (2 papers, 2021 to 2024). A chronic inflammatory process causing damage and fibrosis of the pancreatic parenchyma. "Afterwards, a study including 104 PDAC patients, 60 chronic pancreatitis patients, and five patients with benign gallstone disease focused on the methylation status of NPTX2." (PMID 34968295, 2021). "Another group found SPARC and NPTX2 hypermethylation can distinguish PDAC from healthy controls and patients with chronic pancreatitis." (PMID 39409954, 2024). "NPTX2 hypermethylation was found in pretreatment plasma from 84% of PDAC patients, 33% of patients with chronic pancreatitis and none of the patients with benign gallstone disease (p-value = 0.016)." (PMID 34968295, 2021).
cortical atrophy (2 papers, 2020 to 2025). "This is supported by the finding that reduced CSF NPTX2 levels were associated with increased cortical atrophy and reduced glucose metabolism in temporal and parietal regions of the brain, regions that are particularly susceptible to AD pathology." (PMID 32807227, 2020). "Nevertheless, the inverse relationship we report between CSF NPTX2 levels and a neuroimaging marker of cortical atrophy, suggests that neurodegeneration has a discernable but limited confounding effect on CSF NPTX2 levels." (PMID 32807227, 2020). "When taken together with the significant association observed with cortical atrophy in AD patients, this suggests that the reduced levels of CSF NPTX2 are not due to neurodevelopmental factors but rather due to synaptic loss and dysfunction in AD patients." (PMID 40522075, 2025).
depression (2 papers, 2019). "Moreover, it would be of interest to further investigation the interaction between miR-301b and NPTX2 and the underlying mechanism by which activated microglia and inflammatory factors work to influence the incidence and development of depression." (PMID 30962417, 2019). "Among the DEGs, the NPTX2, Sri and hemoglobin Subunit Beta-b2 (Hbb-b2) genes were relatively more central, which exhibited evident interaction with the known genes of depression." (PMID 30962417, 2019). "In order to further elucidate the functions of NPTX2 in depression, the RNA22 and microRNA.org databases were applied to predict the regulatory miRNAs of NPTX2 in mice." (PMID 30962417, 2019). "Microarray-based prediction identified the differentially expressed gene neuronal pentraxin II (NPTX2) related to mental depression." (PMID 30962417, 2019). "Existing reports further suggested that the role of NPTX2 in depression may be achieved through the NF-κB signaling pathway." (PMID 30962417, 2019). "The key findings of our study may shed light for future studies investigating the binding of miR-301b to NPTX2 as therapeutic targets for the treatment of depression." (PMID 30962417, 2019). "Owing to these findings, we deemed it is reasonable to hypothesize that miR-301b may affect the progression of depression by regulating NPTX2 and the NF-κB signaling pathway." (PMID 30962417, 2019). "In contrast to the depression group, the miR-301b mimic, miR-301b mimic + SN50 and miR-301b mimic + PLX3397 group exhibited reduced protein expression of NPTX2, while the miR-301b inhibitor group showed elevated levels (p < 0.05)." (PMID 30962417, 2019). "Relative to the depression group, the miR-301b mimic and miR-301b mimic + PLX3397 groups showed obviously decreased expressions of NPTX2, and the miR-301b mimic group displayed increased expressions of p-NF-κB, TNF-α, IL-Iβ, and COX-2 (p < 0.05)." (PMID 30962417, 2019).